TET1 (tet methylcytosine dioxygenase 1)
Description:
Dioxygenase that plays a key role in active DNA demethylation, by catalyzing the sequential oxidation of the modified genomic base 5-methylcytosine (5mC) into 5-hydroxymethylcytosine (5hmC), 5-formylcytosine (5fC), and 5-carboxylcytosine (5caC). In addition to its role in DNA demethylation, plays a more general role in chromatin regulation by recruiting histone modifying protein complexes to alter histone marks and chromatin accessibility, leading to both activation and repression of gene expression. Plays therefore a role in many biological processes, including stem cell maintenance, T- and B-cell development, inflammation regulation, genomic imprinting, neural activity or DNA repair. Involved in the balance between pluripotency and lineage commitment of cells and plays a role in embryonic stem cells maintenance and inner cell mass cell specification. Together with QSER1, plays an essential role in the protection and maintenance of transcriptional and developmental programs to inhibit the binding of DNMT3A/3B and therefore de novo methylation. May play a role in pancreatic beta-cell specification during development. In this context, may function as an upstream epigenetic regulator of PAX4 presumably through direct recruitment by FOXA2 to a PAX4 enhancer to preserve its unmethylated status, thereby potentiating PAX4 expression to adopt beta-cell fate during endocrine lineage commitment. Under DNA hypomethylation conditions, such as in female meiotic germ cells, may induce epigenetic reprogramming of pericentromeric heterochromatin (PCH), the constitutive heterochromatin of pericentromeric regions. PCH forms chromocenters in the interphase nucleus and chromocenters cluster at the prophase of meiosis. In this context, may also be essential for chromocenter clustering in a catalytic activity-independent manner, possibly through the recruitment polycomb repressive complex 1 (PRC1) to the chromocenters (By similarity). During embryonic development, may be required for normal meiotic progression in oocytes and meiotic gene activation (By similarity). Binds preferentially to DNA containing cytidine-phosphate-guanosine (CpG) dinucleotides over CpH (H=A, T, and C), hemimethylated-CpG and hemimethylated-hydroxymethyl-CpG. [Isoform 1]: Dioxygenase that plays a key role in active DNA demethylation. Binds to promoters, particularly to those with high CG content (By similarity). In hippocampal neurons, isoform 1 regulates the expression of a unique subset of genes compared to isoform 2, although some overlap exists between both isoforms, hence differentially regulates excitatory synaptic transmission (By similarity). In hippocampal neuron cell cultures, isoform 1 controls both miniature excitatory postsynaptic current amplitude and frequency (By similarity). Isoform 1 may regulate genes involved in hippocampal-dependent memory, leading to positive regulation of memory, contrary to isoform 2 that may decrease memory (By similarity). [Isoform 2]: Dioxygenase that plays a key role in active DNA demethylation. As isoform 1, binds to promoters, particularly to those with high CG content, however displays reduced global chromatin affinity compared with isoform 1, leading to decreased global DNA demethylation compared with isoform 1 (By similarity). Contrary to isoform 1, isoform 2 localizes during S phase to sites of ongoing DNA replication in heterochromatin, causing a significant de novo 5hmC formation, globally, and more so in heterochromatin, including LINE 1 interspersed DNA repeats leading to their activation (By similarity). In hippocampal neurons, isoform 2 regulates the expression of a unique subset of genes compared to isoform 1, although some overlap between both isoforms, hence differentially regulates excitatory synaptic transmission (By similarity). In hippocampal neuron cell cultures, isoform 2 controls miniature excitatory postsynaptic current frequency, but not amplitude (By similarity). Isoform 2 may regulate genes involved in hippocampal-dependent memory, leading to negative regulation of memory, contrary to isoform 1 that may improve memory (By similarity). In immature and partially differentiated gonadotrope cells, directly represses luteinizing hormone gene LHB expression and does not catalyze 5hmC at the gene promoter (By similarity).
Synonyms: CXXC6; KIAA1676; LCX; bA119F7.1
Tractability: Small molecule: a high-quality ligand is known. PROTAC: UniProt records ubiquitination sites on it; ubiquitination databases record sites on it; a small molecule that binds it is known.
Target class: Enzyme; Oxidoreductase
Gene: Protein-coding gene on chromosome 10 (68,560,310 to 68,694,586, forward strand). Ensembl gene ENSG00000138336.
Subcellular location: Nucleus; Chromosome; Nucleus (Isoform 1); Nucleus (Isoform 2)
Subcellular location (Human Protein Atlas): Nucleoplasm; Nuclear membrane
Pathways (Reactome):
Gene expression (Transcription): TET1,2,3 and TDG demethylate DNA
Gene Ontology:
Molecular function: DNA 5-methylcytosine dioxygenase activity; DNA binding; iron ion binding; methyl-CpG binding; protein binding; RNA polymerase II cis-regulatory region sequence-specific DNA binding; zinc ion binding; 2-oxoglutarate-dependent dioxygenase activity
Biological process: cellular response to reactive oxygen species; chromatin remodeling; positive regulation of gene expression via chromosomal CpG island demethylation; positive regulation of transcription by RNA polymerase II; inner cell mass cell differentiation; negative regulation of cell migration; negative regulation of stem cell population maintenance; negative regulation of transcription by RNA polymerase II; negative regulation of transforming growth factor beta receptor signaling pathway; positive regulation of stem cell population maintenance; protein O-linked glycosylation; stem cell population maintenance; epigenetic regulation of gene expression; regulation of gene expression
Cellular component: chromosome; nuclear membrane; nucleoplasm; nucleus; Sin3-type complex
Genetic constraint (gnomAD): Loss-of-function variants: 13 observed, 136.72 expected, observed/expected ratio (o/e) 0.0951, 90% interval 0.061 to 0.15. The upper end of that interval is the gene's LOEUF score, 0.15, which puts it in group 1 of 6, group 1 being the genes least tolerant of losing a copy. Missense variants: 2,130 observed, 2,612.2 expected, observed/expected ratio (o/e) 0.82, 90% interval 0.79 to 0.85. Synonymous variants: 888 observed, 965.26 expected, observed/expected ratio (o/e) 0.92, 90% interval 0.87 to 0.97.
Cancer hallmarks: suppression of growth (promotes); invasion and metastasis (promotes); invasion and metastasis (suppresses); escaping programmed cell death (suppresses)
Homologues: Orthologues: chimpanzee TET1 (99% identical), macaque TET1 (96% identical), dog TET1 (80% identical), pig TET1 (78% identical), rabbit TET1 (74% identical), guinea pig TET1 (62% identical), rat Tet1 (55% identical), mouse Tet1 (54% identical), zebrafish tet1 (25% identical). Paralogues in human: TET2 (22% identical), TET3 (21% identical).
Diseases named in the same sentence as TET1 in open-access papers:
TET1 is named in the same sentence as 249 diseases in open-access papers, as found by Europe PMC text mining. Sharing a sentence is not in itself a finding about the gene and the disease. The quoted sentences say what the papers report.
breast cancer (83 papers, 2013 to 2025). A primary or metastatic malignant neoplasm involving the breast. "In 2015, Sang et al33 observed that TET1 down-regulation via siRNA inhibited breast cancer cell invasion and was associated with lymph node metastasis." (PMID 40520993, 2025). "While TET2 and TET3 have the potential to influence estrogen receptors and luminal-like transformation in breast cancer, TET1 appears to be more associated with hormone-independent breast cancer." (PMID 39201247, 2024). "The overexpression of the long isoform of TET1 was found to be associated with the inhibition of the cell oncogenic phenotype in breast cancer." (PMID 39201247, 2024). "Several studies demonstrated a positive association between high expression levels of TET1 and better overall survival of breast cancer patients and the opposite was also reported whereby low levels of TET1 was associated with worse overall survival." (PMID 34209564, 2021). "In the pooled analysis, higher TET1 expression in cancer was associated with better overall survival (OS) and in subgroup analysis higher TET1 expression was associated with better OS in respiratory tumors as well as in breast cancer from Asian patients." (PMID 34209564, 2021). "TET1 loss in prostate cancer and breast cancer was found contributing to the hypermethylation of tissue inhibitors of metalloproteinases genes (TIMP2 and TIMP3), which resulted in the epithelial-mesenchymal transition (EMT) and tumor progression." (PMID 34957093, 2021). "For breast cancer, reduced %5-hmC was assessed as a biomarker of tumor development, and TET1 decreases were linked to poor prognosis." (PMID 27980696, 2016). "In earlier studies, decreased TET1 mRNA levels in breast cancer were associated with increased invasiveness and metastasis in vitro and in vivo." (PMID 25557833, 2015). "In early-stage breast cancer patients, low levels of TET1 mRNA were associated with poor survival rates, and in breast cancer cell line and mouse xenograft models, TET1 was reported to regulate tumor growth and metastasis by demethylating HOXA7 and HOXA9 promoter regions." (PMID 36979633, 2023). "In addition, it was found that reduced expression of TET1 is associated with poor prognosis of early breast cancer patients." (PMID 35646706, 2022). "In addition, TET1 repression has also been associated with increased tumor-infiltrating immune cells in several cancer types such as basal-like breast cancer (BLBC), melanoma, ovarian, lung and thyroid cancer." (PMID 34298712, 2021). "The implication of TET proteins in breast cancer growth and metastasis has been strongly documented, and the level of hypomethylation of triple-negative breast cancer has been associated with TET1 DNA demethylase activity." (PMID 31611907, 2019). "In a small subset of breast cancers, loss of 5hmC occurs via decreased TET1 expression." (PMID 29593282, 2018). "Therefore, the prognostic value of this association between TET1 and overall survival might only hold true in the Asian dataset and should be cautiously inferred and interpreted in the context of other breast cancer datasets and subtypes." (PMID 34209564, 2021). "In 2020, Yan et al28 demonstrated that TET1 expression is reduced in urinary breast cancer samples compared with normal urothelium." (PMID 40520993, 2025). "In breast cancer, hypoxia induced upregulation of TET1/TET3 transcription and increased 5hmC levels were reported to drive metastatic transformation and poor prognosis." (PMID 40241172, 2025). "In tumor tissues, researchers found that reduced TET1 expression led to lower levels of 5hmC and mRNA for LZTS1, a well-known tumor suppressor gene associated with breast cancer progression and metastasis." (PMID 40014756, 2025). "To investigate the role of TET1 in regulating SMAD/TGF-β pathway genes in CAFs, we analyzed the correlation between promoter DNA methylation and gene expression of the SMAD/TGF-β pathway in relation to TET1 expression in breast cancer." (PMID 40216762, 2025).
breast cancer (continued). "In 2012, Hsu and his team discovered that TET1 suppressed tumour invasion and metastasis in breast cancer by deterring the genes of tissue inhibitors of metalloproteinases from being methylated." (PMID 40014756, 2025). "This decrease is associated with tumor stage, grade, and overall survival, suggesting TET1's potential involvement in urinary breast cancer progression." (PMID 40520993, 2025). "These inhibitors are being investigated for use in TET1-altered diseases, including breast cancer, acute myeloid leukemia, and T-cell acute lymphoblastic leukemia." (PMID 40520993, 2025). "It has been shown that reducing TET1 expression enhances cell invasion, metastasis, and tumor growth in xenograft models, which correlates with poorer survival in breast cancer patients." (PMID 40520993, 2025). "In these studies, the switch between carcinogenic and anticancer properties of TET1 highlights the complex network of relationships between TET1 and breast cancer." (PMID 40599235, 2025). "miR-29a has been shown to promote migration and invasion in breast cancer cells by targeting ten-eleven translocation 1 (TET1), thereby activating epithelial-mesenchymal transition (EMT)." (PMID 40958878, 2025). "Consistent with the oncogenic mechanisms mentioned earlier in breast cancer, TET1 also inhibits tumor cell invasion by activating TIMPs, whose depletion promotes prostate cancer invasion and metastasis." (PMID 40599235, 2025). "Down-regulation of TET1 led to increased invasiveness and cell proliferation in urinary breast cancer cells while restoring normal TET1 expression counteracted these effects and suppressed tumor growth in animal models." (PMID 40520993, 2025). "Then we compared their expression in different subtypes of breast cancer and found only TET1 was specifically highly expressed in BLBC." (PMID 38491910, 2024). "In breast cancer, TET1 has been shown to impair HOXA7 function by modulating HOXA promoters, thereby promoting breast tumor growth and metastasis." (PMID 39596630, 2024). "The bivalent gene POU4F1 is epigenetically activated in basal‐like breast cancer by DNA demethylase TET1." (PMID 38491910, 2024). "In the current work we demonstrate the presence of a heterogenous expression level and localization of TET1 in breast cancer samples." (PMID 35646706, 2022). "In this sense, our results are in agreement with different studies that have shown that TET1 expression is variable between different subtypes of breast cancer or in the same subtype of cancer that have specific molecular markers." (PMID 35646706, 2022). "Of course, this conclusion is an indication that the expression level and pattern of TET1 isoforms is different between different types of breast cancer." (PMID 35646706, 2022). "We also show that while all TET1 isoforms are almost depleted in a basal breast cancer animal model, the expression of the short isoform is induced in luminal breast cancer model." (PMID 35646706, 2022). "Global loss of 5-hmC is found to be associated with the downregulation of TET1 and TET3 genes in breast cancer." (PMID 36230901, 2022). "It has been reported that miR-22 directly targets and reduces TET1 expression, which results in significantly lower global 5hmC and promotes breast cancer EMT and metastasis in mouse xenograft models, making itself a potential target for cancer therapies." (PMID 35805009, 2022). "Of course, these results don’t preclude that the short isoform is important in the pathogenesis of TNBC but indicates that further studies are needed in order to elucidate the different functions of the TET1 isoforms in different breast cancer types." (PMID 35646706, 2022). "To test the expression pattern of TET1 in breast cancer in patient samples, we stained different types of human breast cancer samples by IHC using antisera against TET1 enzyme." (PMID 35646706, 2022).
breast cancer (continued). "We show that the expression pattern of TET1 in breast cancer tissue samples is very heterogeneous in the sense of expression level and localization." (PMID 35646706, 2022). "In mouse xenografts, TET1 suppresses tumor growth and metastasis by regulating the HMGA2-TET1-HOXA9 pathway, which is implicated in the epigenetic regulation of human breast cancer." (PMID 35646706, 2022). "This controversy in the published literature made it necessary to try to better understand the expression pattern and regulation of the different TET1 isoforms in breast cancer." (PMID 35646706, 2022). "TET1 was shown to be overexpressed in breast cancer and that its knockdown leads to inactivation of PI3K-mTOR pathway." (PMID 35646706, 2022). "In specific, TET1 was also shown to play different roles in different types of cancers including, liver, cervical, gastric, colon and breast cancers." (PMID 35646706, 2022). "Because we noted that TET1 isoforms behave differentlt, and because breast cancer behavior is affected by hormones, we studied the effect of different hormones on the expression of different TET1 isoforms." (PMID 35646706, 2022). "This was demonstrated in two independent studies that investigated the role of TET1 in gastric and breast cancers." (PMID 35646706, 2022). "Although this fact was neglected in many published papers that studied the role of TET1 in breast cancer, it appears that the distribution pattern of TET1 can affect its catalytic function." (PMID 35646706, 2022). "For example, TET1 expression pattern in tissue samples was shown to correlate with poor prognosis in breast cancer patients and that it’s expression is elevated and correlates with the hypoxic level in breast cancer samples." (PMID 35646706, 2022). "The depletion of TET1 in xenograft models promoted breast cancer cell invasion and growth and induced breast cancer cell metastasis." (PMID 34656178, 2021). "In 2012, they demonstrated a tumor-suppressive role of TET1 in breast cancer as knockdown of TET1 by shRNA promotes the invasion and metastasis of breast cancer cells." (PMID 34885145, 2021). "This differential result suggests that the degree of TET1 expression varies among different subtypes of breast cancer." (PMID 34656178, 2021). "Again, their findings also reinforce a subtype-specific role of TET1 in modulating the inflammation and cancer immunity in breast cancer." (PMID 34885145, 2021). "High levels of hypoxia were shown to induce TET1 expression, 5-hmC accumulation, and global DNA hypomethylation in hepatoblastoma cells, breast cancer cells, and other malignancies." (PMID 34440238, 2021). "TET1 decreased expression and low 5-hmC levels are frequently observed in many different types of cancers, including gastric, prostate, liver, lung, and breast cancer as well as glioblastoma and melanoma." (PMID 34948036, 2021). "In this study, it was shown that the basal subtype of breast cancer with low TET1 levels has a high expression of immune markers and immune cell infiltration." (PMID 34209564, 2021). "There are a number of reports demonstrating the oncogenic potential of TET1, in particular in ovarian and breast cancer." (PMID 34844636, 2021). "It has also been demonstrated in vivo that TET1 inhibits of the progression of breast cancer cells, whereas the reduced expression of TET1 in patients with breast cancer correlates with poor survival." (PMID 33182353, 2020). "Multiple cell lines of evidence supported the tumor-suppressive function of TET1 proteins in endocrine carcinomas, such as breast cancer and ovarian cancer." (PMID 32089682, 2020). "For example, in breast cancer, TET1 can demethylate its own promoter and the promoter of HOXA genes, enhancing its own expression and stimulating HOXA7 and HOXA9 expression." (PMID 33375038, 2020). "Accordingly, downregulation of TET1—as is the case in breast cancer—stimulates the WNT pathway due to repression of DKK levels." (PMID 31426393, 2019).